EIF2AK2 (eukaryotic translation initiation factor 2 alpha kinase 2)
Diseases named in the same sentence as EIF2AK2 in open-access papers (continued):
Sharing a sentence is not in itself a finding about the gene and the disease.
Dystonia (10 papers, 2020 to 2025). An abnormally increased muscular tone that causes fixed abnormal postures. "Other dystonia genes with likely pathogenic or pathogenic variants were EIF2AK2 (n = 5 index patients), ANO3 (n = 2), EIF4A2 (n = 1), and TOR1A (n = 1) for genes causing isolated dystonia." (PMID 40533913, 2025). "A subsequent human genetic association of dystonia with mutations in the EIF2AK2 gene, which encodes the PKR kinase, further established the link between dystonia and the ISR." (PMID 38557486, 2024). "For six variants, segregation analysis revealed that the identified variant co‐segregated with the dystonia phenotype in the affected families, supporting its pathogenic role (EIF2AK2:p.Pro31Ser, EIF2AK2:p.Gly130Arg, THAP1:p.Ser51Arg, GCH1:p.Glu61*, SGCE:p.Met174Lys, SGCE:c.233‐1G>A:p.)?" (PMID 40533913, 2025). "Given the role of the eIF2α pathway in regulating neuronal long-term synaptic plasticity, EIF2AK2 variants may represent a direct link between endoplasmic reticulum stress and aberrant synaptic plasticity, a well-established pathophysiological hallmark of dystonia." (PMID 40724495, 2025). "While DYT-PRKRA (OMIM#612067) shows a primary combined dystonia phenotype and is, therefore, discussed in the following section, EIF2AK2-related disorder (OMIM#619687) typically presents as a predominantly isolated dystonia." (PMID 40724495, 2025). "In addition, dysregulation of the integrated stress response has been observed in several monogenic forms of dystonia, including those associated with variants in TOR1A, THAP1, PRKRA, EIF2AK2, and SGCE genes, suggesting a converging pathogenic mechanism." (PMID 40724495, 2025). "EIF2AK2 activity is regulated by interferon-induced double-stranded RNA-dependent protein kinase activator A (PRKRA), and a biallelic variant of PRKRA is a confirmed cause of dystonia (DYT-PRKRA) (DYT-PRKRA)." (PMID 37638318, 2023). "Notably, 43 out of 84 variants (51.2%) in established dystonia genes were not previously reported, including two novel recurrent variants (EIF2AK2:p.Pro31Ser and VPS16:p.Ile484Thrfs*70)." (PMID 40533913, 2025). "The frequencies of these genetic forms in our dystonia sample were 0.9% (17/1895 index patients) for VPS16, 0.3% (5/1895) for EIF2AK2, and 0.05% (1/1895) for EIF4A2." (PMID 40533913, 2025). "Recent discoveries have expanded the genetic landscape of dystonia, identifying novel contributors such as AOPEP, VPS11, VPS16, and EIF2AK2." (PMID 40584247, 2025). "Of these, the genes VPS16, EIF2AK2, and EIF4A2, which were relatively recently associated with dystonia, were not included in the prescreening process." (PMID 40533913, 2025).
mild cognitive impairment (9 papers, 2015 to 2025). "Interestingly, rare mutations in EIF2AK1 and the related gene EIF2AK2 (which encodes the eIF2α kinase PKR) are associated with developmental delay, white matter alterations, cognitive impairment, and movement disorders." (PMID 33168630, 2021).
glioma (6 papers, 2014 to 2023). A benign or malignant brain and spinal cord tumor that arises from glial cells (astrocytes, oligodendrocytes, ependymal cells). "Among prognostic and editing-regulated genes, EIF2AK2 showed the maximum editing difference between high- and low-risk gliomas." (PMID 35406793, 2022). "Genes associated with inflammatory response (e.g., EIF2AK2, a key mediator of innate immunity) and fatty acid oxidation (e.g., acyl-CoA oxidase 1, the rate-limiting enzyme in fatty acid β-oxidation) were editing-regulated and associated with glioma progression." (PMID 35406793, 2022). "We therefore investigated gene expression levels of natural antisense lncRNA CHROMR (Cholesterol Induced Regulator of Metabolism RNA) and its sense protein coding gene PRKRA (Protein Activator of Interferon Induced Protein Kinase EIF2AK2) in gliomas." (PMID 36950523, 2023). "The role of EIF2AK2 in glioma is further supported by the finding that PKR activates nuclear factor-kappa B (NF-κB), which is essential for GBM growth." (PMID 35406793, 2022). "In particular, EIF2AK2 may acts as an editing-regulated mediator of glioma progression given its key role in inflammatory response." (PMID 35406793, 2022). "Collectively, RNA editing of EIF2AK2 may function as a sex-dependent mediator of glioma progression through regulating the mRNA abundance." (PMID 35406793, 2022). "We also showed that IFN receptor (e.g., IFNAR1) and ISGs (e.g., EIF2AK2 and MAVS) were prognostic and editing-regulated in glioma." (PMID 35406793, 2022). "As activated PKR inhibits cell growth, it is surprising to note that EIF2AK2 expression is significantly higher in gliomas compared to non-tumoral brain tissues." (PMID 31795417, 2019). "However, as PKR activation is necessary for eIF2α phosphorylation, it is possible that assessing the expression of its gene EIF2AK2 is not sufficient to assess its function in gliomas." (PMID 31795417, 2019).
prion disease (6 papers, 2013 to 2023). A transmissible disease that is caused by a protein that is able to induce abnormal folding of normal cellular proteins, leading to characteristic spongiform brain changes, which are associated with neuronal loss without an inflammatory response. "The Eif2ak2 gene product PKR has been shown to be capable of phosphorylation of eukaryotic initiation factor 2α (eIF2α), a translational controller which has been proposed to play a key role in the progression of neurodegeneration in models of prion disease." (PMID 30680794, 2019).
atherosclerosis (5 papers, 2015 to 2025). A disease characterized by the build-up of fatty material and calcium deposition in the arterial wall resulting in partial or complete occlusion of the arterial lumen. "Applying MAGEIT to a genome-wide analysis of gene–alcohol interactions on hypertension and seated systolic blood pressure in the Multiethnic Study of Atherosclerosis revealed genes like EIF2AK2, CCNDBP1, and EPB42 influencing blood pressure through alcohol interaction." (PMID 39538414, 2025).
dementia (5 papers, 2017 to 2024). Loss of intellectual abilities interfering with an individual's social and occupational functions. "Analysis of kinases, phosphatases, and related signaling factors also reveals heightened activity of EIF2AK2 in patients with HIV-associated dementia compared to those with mild neurocognitive disorder." (PMID 38601162, 2024).
endotoxemia (4 papers, 2016 to 2022). "Pharmacologic or genetic inhibition of PKM2 or EIF2AK2 hampers NLRP3 inflammasome activation and protects mice from lethal endotoxemia and polymicrobial sepsis." (PMID 34697412, 2022).
asthma (3 papers, 2021 to 2023). "In terms of host genetics, polymorphisms in several antiviral and innate immune genes, including STAT4, JAK2, MX1, VDR, DDX58, and EIF2AK2, were linked to susceptibility to respiratory viruses, infection severity, and virus-induced asthma exacerbations." (PMID 36077310, 2022).
encephalitis (3 papers, 2013 to 2022). An acute inflammatory process affecting the brain parenchyma. "Nevertheless at 14 dpi, BeAn-infected IFN-β-/- mice showed a stronger encephalitis and astrogliosis, higher viral load as well as higher mRNA levels of Isg15, Eif2ak2 (PKR), Tnfa, Il1b, Il10, Il12 and Ifng in the cerebrum than BeAn-infected WT mice." (PMID 35222374, 2022).
generalized dystonia (3 papers, 2022 to 2025). "EIF2AK2, which encodes the protein kinase PKR involved in the integrated stress response, has been recently associated with early-onset generalized dystonia." (PMID 40584247, 2025). "The most recent evidence for the role of the elF2α pathway stems from the discovery of pathogenic variants in a member of the eIF2α kinases family, EIF2AK2 (Eukaryotic translation initiation factor 2 alpha kinase 2), in early-onset generalized dystonia." (PMID 38835919, 2022).
head and neck cancer (3 papers, 2011 to 2021). A primary or metastatic malignant neoplasm affecting the head and neck. "It is of interest, then, that increased expression of PKR (eIF2AK2), a kinase that phosphorylates eIF2α, and of eIF2A, the recruiter of alternate tRNAi, occur in a majority of head and neck cancers (TCGA dataset) and that they significantly correlate with poor survival of HNSCC patients." (PMID 35048066, 2021).
non-small cell lung carcinoma (3 papers, 2011 to 2022). A group of at least three distinct histological types of lung cancer, including non-small cell squamous cell carcinoma, adenocarcinoma, and large cell carcinoma. "This agrees with the finding that editing of the 3′UTR of EIF2AK2 increased endogenous EIF2AK2 mRNA abundance in non-small cell lung carcinoma." (PMID 35406793, 2022). "The phosphorylation of EIF2A as well as the activation of eukaryotic translation initiation factor 2-alpha kinase 2 (EIF2AK2, best known as PKR) have been associated with favorable disease outcome in a cohort of 193 non-small cell lung carcinoma (NSCLC) patients." (PMID 26300886, 2015).
type 1 diabetes (3 papers, 2019 to 2022). "EIF2AK2 was overexpressed in islets of type 1 diabetes patients." (PMID 31881887, 2019).
heart failure (2 papers, 2022 to 2025). Inability of the heart to pump blood at an adequate rate to meet tissue metabolic requirements. "In the validation set GSE5406, the expression of JAK1 was dramatically downregulated, while EIF2AK2 was significantly upregulated in heart failure (HF) tissues." (PMID 39704101, 2025).
Hypertension (2 papers, 2024 to 2025). The presence of chronic increased pressure in the systemic arterial system. "EIF2AK2 encodes the protein kinase R (PKR) on chromosome 2, which animal studies have shown may affect hypertension through modulation of angiotensinogen and TGF-β, reducing fibrosis and apoptosis." (PMID 39538414, 2025).
pulmonary hypertension (2 papers, 2020 to 2025). Increased pressure within the pulmonary circulation due to lung or heart disorder. "Among these proteins, we selected HMOX1 (or HO-1) and IFIT3 for confirmation by the semi-quantitative Western blot approach to confirm these findings due to the importance of HMOX1 and EIF2AK2 (or PKR) in the pulmonary field and due to the novelty of IFIT3 in the pulmonary hypertension field." (PMID 33036472, 2020).
Stroke (2 papers, 2025). Sudden impairment of blood flow to a part of the brain due to occlusion or rupture of an artery to the brain. "Machine learning technique, LASSO regression analysis, was utilized to refine our search, leading to the identification of three genes, EIF2AK2, PARP9, and IFI27, which demonstrated strong diagnostic potential confirmed by ROC curves in both stroke and SLE cohorts." (PMID 40313968, 2025). "In the stroke-GSE16561 dataset, the AUC values for EIF2AK2, PARP9, and IFI27 were 0.862, 0.797, and 0.685, respectively, all exceeding 0.6." (PMID 40313968, 2025). "In the stroke validation set (GSE58294), the AUC values for EIF2AK2, PARP9, and IFI27 were 0.761, 0.689, and 0.584, respectively." (PMID 40313968, 2025). "This study marks the first exploration of hub genes in the context of stroke and SLE, suggesting EIF2AK2, PARP9, and IFI27 as potential biomarkers for further investigation into the mechanistic underpinnings of their comorbidity." (PMID 40313968, 2025). "The correlation analysis indicated an inverse relationship between the genes EIF2AK2, PARP9, and IFI27 and the presence of M2 macrophages within the stroke dataset." (PMID 40313968, 2025). "Together, these hub genes (EIF2AK2, PARP9, and IFI27) are integral to the regulation of autoimmune and inflammatory responses, representing potential biomarkers for SLE with concomitant stroke." (PMID 40313968, 2025). "Therefore, we validated EIF2AK2, PARP 9 and IFI 27 as hub genes in the progression of stroke." (PMID 40313968, 2025). "The results showed that the expression of EIF2AK2, PARP 9 and IFI 27 was consistent with our DEGs analysis, and the gene expression was increased in stroke mice compared with non-infarcted area." (PMID 40313968, 2025).
bacterial sepsis (1 paper, 2024). "While Eif2ak2 and Herc6 are implicated in bacterial sepsis, Rnf213 is associated with ubiquitylation of LPS, and Casp1 is a key factor in the inflammatory response in bacterial infection as detected in common upregulation." (PMID 38792580, 2024).
coronary artery disease (1 paper, 2021). "However, cytoplasmic signal transducer and activator of transcription 3 is encoded by STAT3 dampens macroautophagy by repressing EIF2AK2/PKR activity, while its gene expression is also increased dramatically in patients with coronary artery disease." (PMID 34012683, 2021).
Pulmonary capillary hemangiomatosis (1 paper, 2021). Pulmonary capillary hemangiomatosis (PCH) is a rare form of pulmonary arterial hypertension (PAH, see this term) characterized by a capillary infiltration of the pulmonary interstitium, bronchioles and pleura leading to elevated pulmonary arterial resistance and right heart failure. "EIF2AK2 is homologous to the known PAH pathogenic gene EIF2AK4, a diagnostic marker of pulmonary venous occlusive disease and pulmonary capillary hemangiomatosis." (PMID 34336829, 2021).
schizophrenia (1 paper, 2015). A major psychotic disorder characterized by abnormalities in the perception or expression of reality. "Analysis in schizophrenia genome-wide association data from the Psychiatric Genetics Consortium specifically implicated eIF2α regulatory kinase EIF2AK2, and confirmed the importance of the eIF2α, eIF4 and mTOR translational control pathways at the level of the genome." (PMID 26485547, 2015).
scrapie (1 paper, 2007). A fatal disease of the nervous system in sheep and goats, characterized by pruritus, debility, and locomotor incoordination. "Similarly, no further increase in Eif2ak2 expression was observed in the mouse model of BSE, but a statistically significant 67% increase in Eif2ak2 expression (p = 0.00052) was observed in the scrapie mouse model." (PMID 17367538, 2007).
uterine disease (1 paper, 2022). "Pregnancy regulated genes downstream of AIRE in cows following uterine infection are all upregulated (EIF2AK2, IFI44, HERC6, PARP14, TNFSF10), suggesting the dysregulated expression of these genes could be important for pregnancy establishment following uterine disease." (PMID 35358206, 2022).
infection (343 papers, 2005 to 2026). The state of being infected such as from the introduction of a foreign agent such as serum, vaccine, antigenic substance or organism. "EIF2AK2 is a stress- and infection-activated kinase that promotes inflammation by mediating the activation of the transcription factor NF-κB." (PMID 39861106, 2025). "Despite p4A activity, we show that high-dose females are still able to upregulate EIF2AK2 early in infection, resulting in activation of PKR-mediated signaling and apoptosis." (PMID 40611900, 2025). "Further IFN and antiviral related proteins were upregulated upon infection with PeV-A3 (EIF2AK2, STAT1), or PeV-A1 (NCAM1, POM121), and downregulated upon PeV-A1 infection (EIF4G1, UBE2N, RANBP2, FLNA)." (PMID 38514653, 2024). "We observed that eIF2α phosphorylation decreases upon infection despite upregulation in EIF2AK2 expression and phosphorylation." (PMID 32479529, 2020). "While many known ISGs with anti-IAV activity are upregulated in both IAV+ and IAV- cells, Eif2ak2 is infection-specific." (PMID 32790753, 2020). "By day 3 post-infection, qRT-PCR showed a 3-fold increase in the mRNA expression levels of EIF2AK2 in THP-1 macrophages." (PMID 33552025, 2020). "The negative correlation of the darkolivegreen module with dpi suggests EIF2AK2 is likely more highly expressed at earlier times post-infection." (PMID 32117434, 2020). "recently reported that EIF2AK2 mRNA increases during infection with the non-pathogenic Mycobacterium smegmatis." (PMID 34305942, 2021). "Other studies have shown that EIF2AK2 mRNA increases during infection with BCG and M. tuberculosis." (PMID 34305942, 2021). "Moreover, phosphorylation of EIF2AK2 at T451 was augmented in response to infection with either parasite stage." (PMID 32479529, 2020). "As representatives of antiviral ISGs, protein kinase R (PLR; encoded by EIF2AK2), Viperin (encoded by RSAD2) and MX dynamin-like GTPase 1 (MX1) are widely known, and these ISGs strongly inhibit the infection of a broad range of viruses." (PMID 30915053, 2019). "Interestingly, expression of EIF2AK2 was higher for EHI0578Y05 compared to Mon601 infection in two of three Müller cell isolates (isolates 2 and 3), whereas expression was lower for EHI0578Y05 versus Mon601 infection in the third Müller cell isolate (isolate 1)." (PMID 37515098, 2023). "During E30 infection, genes associated with the type I IFN signaling pathway (Isg15, Mx1, Mx2, Sp100, Ifit1, Ifit3, Ifih1, Irf7, Irf9, guanylate-binding proteins 2 [Gbp2], and Stat1) and defense response to viruses (Ddx58, Ddx60, Zbp1, Oas2, Nlrc5, and Eif2ak2) were significantly upregulated." (PMID 36147849, 2022). "In contrast, infection with RVA strains G9P{13] led to significant downregulation of the expression of MX1 (both viruses) and EIF2AK2 (PKR) (G9P only)." (PMID 37848925, 2023). "In contrast to infection by SARS-CoV, infection by SARS-CoV 2 led to phosphorylation of the antiviral kinase EIF2AK2 (PKR) at the critical regulatory residue S3328." (PMID 34208880, 2021). "We observed approximately 0.5 to 1-log fold greater expression of ISG15, EIF2AK2, OAS1, IFNA4, and IFNB1 in the lungs of rWSN-GH-NS1-Y84F infected mice on days 1 and 3 post-infection compared with the lungs of rWSN-GH-NS1-wt infected mice." (PMID 28498306, 2017). "Proteomic data from PBMCs collected at 0, 3, and 6 dpi confirmed that both strains induced activation of intracellular sensors (RIG-I, OAS1, and TRIM25) and transcriptional factors such as EIF2AK2, although activation was consistently stronger during MA08 infection." (PMID 39992151, 2025). "Finally, a large cluster, especially in terms of small RNA regulation upon infection, was “cell proliferation, anti-apoptosis, and oncogenesis,” where EIF2AK2, BIRC3, and TXNIP were significantly upregulated upon infection." (PMID 40510596, 2025).
infection (continued). "PKR, also known as eukaryotic initiation factor 2-alpha kinase 2 (EIF2AK2), is another such sensor projected to be an adept regulator of innate immunity and downstream protein translation, against pathogen infection in higher eukaryotes." (PMID 31482095, 2019). "We show that the expression of the interferon-stimulated proteins MX1, IFIT1, IFIT3 and ISG15, as well as expression of defense response proteins DDX58, STAT1, OAS3, EIF2AK2 and SAMHD1 was significantly up-regulated in these cells upon infection with either virus." (PMID 30959732, 2019). "Additionally, we observed increases in the expression of EIF2AK2 (24-fold), OAS1 (10-fold), IFNA4 (10-fold) and IFNB1 (10-fold) in the lungs of rWSN-GH-NS1-Y84F infected mice treated with IFN-β on day 1 post-infection compared with the lungs of infected, but untreated mice." (PMID 28498306, 2017). "In addition to the reported regulatory factors including EIF2AK2, MX, OAS*A, GBP7 and IFIT, IBDV infection also triggered a IFIT5-IRF1/3-RSAD5 pathway in the DF-1 cells which potentially restricted the viral replication cycle in the early infection stage." (PMID 26053856, 2015). "Raymond previously demonstrated that upon IBDV infection, regulatory factors including EIF2AK2, MX, GBP7, and IFIT may trigger the IFIT5-IRF1/3-RSAD5 signalling pathway in DF-1 cells, which potentially restricts viral replication during the early infection stage." (PMID 27816055, 2016).